MYC (MYC proto-oncogene, bHLH transcription factor)
Diseases named in the same sentence as MYC in open-access papers (continued):
Sharing a sentence is not in itself a finding about the gene and the disease.
cancer (continued). "Thirty‐three miRNAs and nineteen lncRNAs are downstream effectors of MYC that contribute to the broad oncogenic role of MYC, including its effects on diverse hallmarks of cancer." (PMID 30451365, 2019). "The transcription factor MYC is overexpressed in many cancers and regulates the expression of multiple genes involved in the determination of cancer cell fate." (PMID 31847321, 2019). "The decreased expression of these miRNAs can thus contribute to the high levels of MYC as commonly observed in cancer." (PMID 30451365, 2019). "The cluster has also been shown to be regulated by bromodomain protein 4 (BRD4) which is increased in MYC-driven cancers." (PMID 31581940, 2019). "WBM-site inhibitors therefore have potential as anticancer agents—being able to directly disrupt the interaction of c-MYC to WDR5 and thus impede the MYC function in cancer cells." (PMID 31768400, 2019). "Numerous pre-clinical studies in a wide array of cancer types have identified MYC as a key target of BET bromodomain inhibition, and our results corroborate those findings." (PMID 30846826, 2019). "In our putative model MYC and LEF1 engage in a positive feedback loop in which oncogenic hits that activate the WNT pathway induce MYC expression in cancer cells." (PMID 31623618, 2019). "One of the mechanisms by which the MYC gene is believed to maintain cancer cell survival is to exempt itself from immune surveillance and the anti-tumor immune response." (PMID 31824865, 2019). "A well‐known exception is miR‐17‐5p, which is part of the oncogenic miR‐17~92 cluster that is often upregulated in MYC‐driven cancers." (PMID 30451365, 2019). "Seminal studies have shown that the proto-oncogene MYC promotes metabolic reprogramming by altering glutamine uptake and metabolism in cancer cells." (PMID 31416966, 2019). "It contains a large number of risk alleles that are implicated in cancer, including the lncRNA Plasmacytoma Variant Translocation 1 (PVT1) as well as an associated protein-coding gene MYC." (PMID 31249809, 2019). "Targets of the MYC proto-oncogene are frequently observed in several human cancers, modulating cell cycle progression, apoptosis and cellular transformation." (PMID 30791886, 2019). "MDM2 is a transcriptional target of MYC, which is frequently overexpressed in human cancers and as a central oncogene/driver in many cancers." (PMID 30816344, 2019). "Although many studies reported that AXT suppresses the expression of NF-κB and STAT3, transcription factors of MYC, to abrogate carcinogenesis in various cancer cells, the detail regulatory mechanisms are still elucidated." (PMID 31263239, 2019). "A novel and promising approach to target MYC-dependent cancer cells is based on interfering with metabolic pathways triggered by hyperactivated MYC." (PMID 31416966, 2019). "In one hand, in short-term treatments the inhibitory effect of rapamycin over cancer cells is mediated by increased expression of let-7 members that regulates c-MYC post-transcriptionally regulates c-MYC." (PMID 31921661, 2019). "First discovered in the 1980s, c-MYC is a pivotal regulator in tumorigenesis of up to 70% of all cancers." (PMID 30683916, 2019). "Elevated expression of c-MYC predicts aggressive disease and a poor clinical outcome in many cancers as well as in cSCC." (PMID 30683916, 2019). "In proscillaridin A-resistant and low expressing MYC cancer cells, histone acetylation levels were unchanged in SW48 cells after treatment, which correlated with our previous report." (PMID 31196146, 2019). "We also found that gene fusion of PVT1 with its neighboring gene MYC is most common in 8q24-amplified cancers." (PMID 31309249, 2019). "As the overexpression of the c-MYC is served in various human malignancies (particularly in 80% of solid tumors), downregulation of the gene is an effective approach to cancer therapy." (PMID 30682877, 2019).
cancer (continued). "When the expression levels of these genes in the different FMCs samples was evaluated, a strong positive correlation was observed between almost all the cancer-related genes under study (except for c-MYC and PKM2)." (PMID 31461477, 2019). "In multiple types of cancer, silencing of MYC leads to a significant reduction in the transcription and expression of CD47 and PDCD1L1, both in vitro and in vivo." (PMID 31824865, 2019). "MYC- and MYC-associated eRNA (MYCe, ENSR00000333355) are positively correlated in six cancer types, and Hi-C data supports their interaction in all 20 tissues." (PMID 31594934, 2019). "The authors quantified and visualized inherent network structures by using R code and identified a subnetwork containing a large number of shared, targeting miRNAs, of genes related to cancer and cellular proliferation, including cyclin D and c-MYC." (PMID 31007608, 2019). "G4 ligands, such as pyridostatin (PDS), PhenDC3 and TMPyP4, can reduce transcription of many genes harbouring a promoter G4, including oncogenes such as MYC, in multiple cancer cell lines." (PMID 31287417, 2019). "For the lymphoid-derived cancer cell lines next to the specific surface markers (e.g., CD72, LAIR) associated with T/B-cells, we identified FLT3, HOXA9, MYC, and HEXIM1 as top genes driving the difference between the samples." (PMID 31253180, 2019). "Among these oncoproteins, MYC deregulation occurred in more than half of human cancers and is usually correlated with aggressive phenotypes, drug resistance and unfavorable prognosis." (PMID 31088567, 2019). "With MYC overexpression occurring in most human cancers, this introduces new strategies for cancer treatment." (PMID 30902071, 2019). "Little is known regarding its expression profile in MBC CTCs; nonetheless, MYC inhibitors have been proposed for targeting cancer stem cells in drug-resistant TNBC." (PMID 31817194, 2019). "As a transcription factor, FOXM1 has many target genes including KIF20A, CENPF, CCNB1, MYC, NIMA-related kinase 2, MMP2, MMP9, and S-phase kinase-associated protein 2 that are implicated in cancer initiation, progression, or drug resistance." (PMID 31072351, 2019). "MYC is a key oncogene that controls several cellular pathways relevant to cancer, including cell cycle entry, ribosome synthesis, and various metabolic processes." (PMID 30635567, 2019). "MYC is one of the most dysregulated oncogenes, including translocation and copy number alteration, in various types of cancers." (PMID 31905596, 2019). "In summary, we have used an in vivo shRNA screening approach to uncover a novel splicing-dependent mechanism for the control of MYC activity which appears to be operative in primary cancer." (PMID 30635567, 2019). "In normal cells, MYC is a transient protein that is present from 20 to 30 min and is uncontrollable in cancers." (PMID 31311829, 2019). "In particular, genes like MYC, MKI67, CTNNB1, PCNA, NKX3.1, ACPP and kallikreins are warranted further investigation as diagnostic markers for cancer and cell proliferation." (PMID 31519932, 2019). "Copy number variations in MYC occur very frequently among other genetic events leading to human cancers, for example, in PDAC." (PMID 31614829, 2019). "BUD31 is a core splicing factor essential for spliceosome assembly, catalytic activity and associates with multiple spliceosome sub-complexes and has shown to be a MYC target in MYC-driven cancer cells." (PMID 31278301, 2019). "c-MYC is among the most frequently affected genes in human cancers, and has a pivotal function in growth control, differentiation and apoptosis and its abnormal expression is associated with many tumors." (PMID 31024927, 2019).
cancer (continued). "Further, in contrast to data found in cancer cells, mTOR activity was dispensable for MYC protein induction in naive and memory murine T cells, regulating PRMT5 expression via downregulation of Prmt5-targeting miRNAs or alternate mechanisms." (PMID 30941147, 2019). "This enhances the expression of the MYC oncogene in cancer cells, as previously reported in EOC- and HCC-derived cancer cells." (PMID 30371874, 2019). "MYC upregulation as a result of JQ1 treatment has also been observed in cell line models of other cancer types, including lung cancer." (PMID 30846826, 2019). "This study highlights a novel therapeutic approach to target highly aggressive and chemoresistant MYC-activated cancers." (PMID 30076412, 2019). "MYC overexpression has been detected in 50–60% of human cancers and plays an essential role in cancer initiation and maintenance through multiple molecular mechanisms including gene amplification, aberrant transcription activation and enhancer hijacking." (PMID 31127282, 2019). "For this reason, we evaluated changes in proteins and transcription factors implicated in increasing VEGF expression in several models of cancer cells, such as c-MYC, β-catenin, and survivin." (PMID 31817839, 2019). "Three recent studies, mainly in MYC‐driven cancers, have uncovered potential mechanistic explanations." (PMID 31334570, 2019). "Dysregulation of this pathway leads to the activation of proto-oncogenes (c-MYC) and cyclin-dependent kinases (Cyclin D1), which eventually leads to cancer cell proliferation." (PMID 31783627, 2019). "Consistently, we demonstrate that chronic stress increases epinephrine levels to promote tumorigenesis and cancer stem-like traits via activation of the LDHA/USP28/MYC/SLUG signaling axis in a mouse model." (PMID 30688660, 2019). "Hyperactivated MYC is a common feature of many malignancies, and studies have demonstrated that MYC depletion mostly results in the inhibition of purine synthesis and growth suppression in various types of cancer cells." (PMID 31108873, 2019). "CDK5 phosphorylates a diverse list of substrates, implicating that it can regulate various cellular processes including the function of c-MYC, which is a crucial transcription factor in cancer." (PMID 31496920, 2019). "E2F4 has also been found with the MYC transcriptional activator at regulatory regions of genes involved in cancer development." (PMID 31270324, 2019). "Together, these studies highlight the need to develop new strategies to abrogate MYC addiction in cancer." (PMID 31196146, 2019). "Given the links between NF-κB/MYC signaling and PRMT5 induction in cancer as well as between NF-κB/MYC and MS, it is important to investigate the impact of these pathways in T cell PRMT5 expression and pathogenic T cell responses." (PMID 30941147, 2019). "One previous study demonstrated that TIMELESS supports cancer cells by increasing MYC expression and activity." (PMID 30629587, 2019). "Among these genes, the ATM and MYC co-appear with item ‘cancer’ for 1377 and 1978 times, with ‘breast’ for 408 and 383 times respectively." (PMID 31088372, 2019). "Cancer cells require this regulatory mechanism because c-MYC overexpression induces apoptosis of cancer cells under glucose deprivation." (PMID 31739577, 2019). "It has been shown in some cancer cell lines that suppression of MYC with BET inhibitors such as JQ1 reduced programmed cell death ligand 1 (PD-L1) and CD47 expression." (PMID 31288832, 2019). "MYC is a family of protooncogenes (i.e., c-MYC, L-MYC and N-MYC) which encode transcription factors that have roles in both normal and cancer cell physiologies." (PMID 31341534, 2019). "MYC is a master regulator of cellular metabolism, and the genes transcriptionally regulated by MYC are critical for the metabolic reprograming of cancer cells." (PMID 31623618, 2019). "The addition to TEM to MP1 was a reasonable strategy based on the activation of TORC1 pathways in MYC amplified cancers." (PMID 31455317, 2019).
cancer (continued). "Previous studies have reported the MYC promoter is physically recruited to a variety of proximal and distal enhancers to enforce its high expression in different human cancer cells." (PMID 31127282, 2019). "In MYC-driven cancers, MYC deregulation affects gene expression, DNA replication, or repair processes, leading to oncogenic proliferation." (PMID 31848373, 2019). "CCAT1-L overexpression resulted in higher MYC expression and faster cell growth than that in the control cancer cell group." (PMID 31824865, 2019). "Among those clinically actionable genes, we demonstrated the functional roles of circMYC to increase cell proliferation through mediating MYC gene, a key oncogene across multiple cancer types." (PMID 31446897, 2019). "WDR5 is a principal component of the H3K4me3 writer complex MLL–SET1 and interacts with MYC oncoprotein, allowing MYC to select its target genes and alter their expression epigenetically in cancer." (PMID 31920530, 2019). "We identify specific proteins controlled by the HSP70/BAG1S chaperone complex that contribute to MYC-driven pro-survival in cancer cells." (PMID 30902071, 2019). "MYC deregulation occurs in the majority of human cancers and is therefore an ideal therapeutic target." (PMID 31350286, 2019). "The nucleolar protein SCFFbw7, a member of SCF family of ubiquitin E3 ligases, using a similar molecular mechanism, regulates some proteins required for cancer cell proliferation like Cyclin E and MYC." (PMID 31527430, 2019). "The bromodomain and extra-terminal (BET) proteins play significant roles in supporting the transcription of known DLBCL oncogene MYC, which provides a way for the development of targeted therapeutic agents to address this kind of malignant tumor." (PMID 31527063, 2019). "Direct targeting of cancer markers such as MYC has been explored to reduce genetic alterations leading to uncontrolled proliferation and metastasis." (PMID 31614829, 2019). "The MYC oncogene is known to be activated in more than 50% of human cancers by multiple mechanisms, and its activation is frequently associated with poor prognosis and unfavorable outcome." (PMID 31731480, 2019). "MYC is a master oncogenic driver, regulating transcriptional programs to influence cell proliferation and metabolism in a variety of human cancers." (PMID 30770740, 2019). "The MYC promoter has been reported to loop to a spectrum of distal and proximal enhancers in different cancers to initiate and maintain tumorigenesis." (PMID 31127282, 2019). "Below, we describe in more detail the MYC‐regulated miRNAs and lncRNAs with a clear role in five main hallmarks of cancer, that is, cell cycle progression, apoptosis, metabolism, angiogenesis, and metastasis." (PMID 30451365, 2019). "As largely reported, the activation of Wnt/β -catenin pathway stimulate the transcription of MYC, and influence growth and metastasis in cancer cells." (PMID 31870402, 2019). "HMGA1 is a stem cell phenotype regulator that targets MYC and is also targeted by MYC, and plays a role in cell growth and invasion in cancer." (PMID 30876441, 2019). "MYC is a transcription factor that de-regulates a wide variety of processes including proliferation, apoptosis, and metabolism, supporting cancer growth." (PMID 31142021, 2019). "MYC, an oncogene that contributes to the progression of many human cancers, has had circRNAs identified in 208 (22.2%) cancer cell lines." (PMID 31446897, 2019).
cancer (continued). "MYC has first been described as a classic transcription factor forming MYC-MAX complexes that binds to E-box19, but an emerging role for MYC as a global regulator of the cancer epigenome and transcriptome is clear." (PMID 31097695, 2019). "As predicted by three online tools including UCSC, JASPAR and PROMO, HOXC-AS1 seemed to be regulated by c-MYC, a well-recognized oncogene in diverse cancers including GC." (PMID 31870402, 2019). "Considering the crucial role of MYC in driving the metabolic reprogramming of cancer which has been shown to be strictly related to drug resistance, several studies have been carried out in order to focus MYC-dependent metabolic pathways." (PMID 31341534, 2019). "The activation and overexpression of MYC is a characteristic feature of tumorgenesis and cancer maintenance." (PMID 31824865, 2019). "The MYC oncogene contributes to the genesis of many human cancers and cMYC is an important prognostic factor in AML." (PMID 31717802, 2019). "Although MYC expression is typically quite high in late-stage human cancers, pronounced overexpression of MYC in normal tissue immediately elicits an apoptotic response, eliminating the offending cells." (PMID 31032816, 2019). "As another example, cancer-risk SNP rs6983267 has been found to increase TCF7L2 binding and enhancer activity to elevate c-MYC expression in colorectal cancer cells." (PMID 30247654, 2019). "For a variety of cancer cells, SEs are found specifically clustered at genes surrounding the MYC gene." (PMID 31824865, 2019). "Targeting GCN5 inhibits both the cancer promoting effects of MYC-driven transcription programs and disrupts PI3K signaling." (PMID 31645904, 2019). "Despite this tight regulation, MYC is overexpressed in many cancers and contributes to multiple hallmarks of cancer." (PMID 30451365, 2019). "Together, we herein established the RTK-initiated transcription regulatory network, which highlighted transcriptional factors ATF4 and MYC as the key nodes in preferentially reprogramming the metabolic network in cancers with aberrant EGFR or FGFR." (PMID 31221965, 2019). "Spliceosome has been previously shown to serve as a novel target of oncogenic stress in c-MYC-dependent cancers, with perturbation of spliceosome in c-MYC-hyperactivated cells resulting in global intron retention." (PMID 30795533, 2019). "Although MYC functions in cancer metabolism are widely recognized, MYC is generally considered ‘undruggable’ largely due to its nuclear localization, lack of an enzymatic ‘active site’, and indispensable roles during normal development." (PMID 31259690, 2019). "The family of the MYC oncogene is deregulated in more than 50% of human cancers and its members participate in many aspects of oncogenesis, such as regulation of proliferation, apoptosis, differentiation, and metabolism of cells." (PMID 31121824, 2019). "The efficacy of BET inhibitors in several types of cancers is dependent on the down-regulation of MYC, an oncogene related to cell cycle progression, apoptosis, and cellular transformation." (PMID 31527063, 2019). "It is worth noting that high level of c-MYC expression results in a significant increase in cancer stem-like cells (CSCs), and drives metabolic reprogramming in TNBC." (PMID 31584090, 2019). "Similar analysis was performed on histone H3 acetylation between high MYC expressing cancer cells versus low MYC expressing cancer cells." (PMID 31196146, 2019). "let-7 miRNAs are important in regulating the cell cycle and maintaining cells’ differentiated state by targeting a wide range of genes with known roles in cancer biogenesis such as MYC/MYCN, RAS, CDK6, and HMGA2." (PMID 31616462, 2019). "These ncRNAs can have profound impacts on MYC levels and activity and can also act downstream of MYC enabling cancer cells to gain the crucial hallmarks of cancer." (PMID 30451365, 2019).